PCDHB9 (protocadherin beta 9)
Description:
Potential calcium-dependent cell-adhesion protein. May be involved in the establishment and maintenance of specific neuronal connections in the brain.
Synonyms: PCDH3H; PCDH-BETA9
Tractability: Antibody: UniProt places it where antibodies can reach, with medium confidence; UniProt predicts a signal peptide or a membrane-spanning region; its Gene Ontology location is reachable by antibodies, with medium confidence.
Gene: Protein-coding gene on chromosome 5 (141,187,127 to 141,191,541, forward strand). Ensembl gene ENSG00000177839.
Subcellular location: Cell membrane
Gene Ontology:
Molecular function: cell adhesion molecule binding; calcium ion binding
Biological process: calcium-dependent cell-cell adhesion; cell adhesion; chemical synaptic transmission; synapse assembly; homophilic cell-cell adhesion; nervous system development
Cellular component: membrane; plasma membrane; synapse
Genetic constraint (gnomAD): Loss-of-function variants: 0 observed, 0.33 expected, observed/expected ratio (o/e) 0, 90% interval 0 to 1.86. That is too few expected variants to judge how well the gene tolerates losing a copy. Missense variants: 1,072 observed, 958.7 expected, observed/expected ratio (o/e) 1.12, 90% interval 1.06 to 1.18. Synonymous variants: 501 observed, 416.99 expected, observed/expected ratio (o/e) 1.2, 90% interval 1.12 to 1.29.
Homologues: Orthologues: chimpanzee PCDHB9 (98% identical), rat AC131360.1 (76% identical), mouse Pcdhb18 (75% identical). Paralogues in human: PCDHB10 (90% identical), PCDHB7 (75% identical), PCDHB14 (74% identical), PCDHB3 (74% identical), PCDHB15 (74% identical), PCDHB11 (73% identical), PCDHB2 (73% identical), PCDHB4 (73% identical), PCDHB13 (73% identical), PCDHB6 (73% identical), PCDHB12 (73% identical), PCDHB5 (72% identical), and 49 more.
Diseases named in the same sentence as PCDHB9 in open-access papers:
PCDHB9 is named in the same sentence as 4 diseases in open-access papers, as found by Europe PMC text mining. Sharing a sentence is not in itself a finding about the gene and the disease. The quoted sentences say what the papers report.
gastric cancer (3 papers, 2019 to 2025). A primary or metastatic malignant neoplasm involving the stomach. "Finally, PCDHB9 upregulation in humans elevates the risk of gastric cancer (the surgical removal of which leads to hypertensive remission) and corresponds to upregulation of β-protocadherins in aggressive rats and wild rabbits during their microevolution." (PMID 35269977, 2022). "Here, we examined the expression of four metastasis-related genes (namely, c-met, HMGB1, RegIV, PCDHB9) in 39 cases of gastric cancer treated with neoadjuvant therapy with CDDP or CDDP+5-fluorouracil and evaluated its association with CDDP responsiveness." (PMID 31905926, 2019).
Hypertension (2 papers, 2022). The presence of chronic increased pressure in the systemic arterial system. "There were 8 differentially methylated genes (CDH2/PCDHB10/PCDHB11/PCDHB14/PCDHB16/PCDHB3/PCDHB6/PCDHB9) in the LAA subgroup and 1 (CDH2) in the SVD subgroup after adjusting for smoking, drinking, history of hypertension and diabetes, and blood lipid levels (p < 0.05)." (PMID 35480311, 2022).
tumor (2 papers, 2005 to 2020). "In oncogenesis, most Pcdhs seem to have a tumor suppressor function, as for several cancer types their downregulation [with the exception of PCDHB9, and PCDH9] correlates with tumor survival." (PMID 32694982, 2020). "Seven of the twelve differential genes found amongst individual tumor ANOVA analyses were common to the linear discriminant gene profile (LD-p54): ANGPLT4, COL1A1, GP2, GPR57, LAMB3, PCDHB9, and PTGER3." (PMID 15836779, 2005).
PCDHB9 also shares sentences with these, for which no sentence is quoted: diabetes (1 paper).